IL6 (interleukin 6)
Diseases named in the same sentence as IL6 in open-access papers (continued):
Sharing a sentence is not in itself a finding about the gene and the disease.
preeclampsia (continued). "In maternal vessels, an increase in pro-inflammatory TNFα and IL6 contributes to causing endothelial dysfunction, which is a hallmark of preeclampsia mainly characterized by reduced production of vasodilation factors and an increase in the permeability of endothelial cells." (PMID 32116801, 2020). "In addition, high levels of interleukin-6 and fibrinogen were associated with a history of early-onset preeclampsia." (PMID 18382655, 2008). "This study was undertaken in women with established preeclampsia therefore, it cannot be determined whether the increase IL-6 was a cause or a consequence of the disease." (PMID 16259641, 2005). "Preeclampsia is characterized by systemic endothelial dysfunction, upregulation of inflammatory cytokines (e.g., IL-6, TNF-α), oxidative stress, and alterations in cerebral microvascular perfusion." (PMID 41517645, 2026). "A recent comprehensive review indicates that most studies found women with preeclampsia exhibit elevated blood levels of cytokines (IL-6, IL-8, TNF-α, and C-reactive protein) compared to normotensive pregnant women." (PMID 41375625, 2025). "The antioxidant vitamin C and the calcium channel blocker nifedipine can inhibit the activation of endothelial cells that phagocytose necrotic trophoblasts, reduce IL6 secretion, and provide a certain preventive or therapeutic effect on preeclampsia." (PMID 39865240, 2025). "These circulating IL6 and TGFβ further activate endothelial cells throughout the body, exacerbating endothelial damage and inflammation in preeclampsia." (PMID 39865240, 2025). "Concurrently, monocytes from women with preeclampsia produce more IL-1 and IL-6 than monocytes from healthy pregnant women." (PMID 41156157, 2025). "Inflammation and systemic immune response: Periodontal infections induce chronic systemic inflammation, increasing the production of pro-inflammatory cytokines (IL-6 and TNF-α) and CRP, which are also implicated in preeclampsia." (PMID 40496368, 2025). "Emerging evidence highlights the role of elevated IL-6 and other cytokines in recurrent miscarriage, preeclampsia and preterm delivery, and in exacerbating neurodegenerative processes via microglial priming and oxidative stress pathways." (PMID 40244235, 2025). "Women with preeclampsia were found to exhibit increased concentrations of interleukin (IL)-1, IL-6, and tumor necrosis factor alpha (TNF-α) in their plasma and amniotic fluid, alongside elevated levels of IL-2 and interferon gamma (IFN-γ)." (PMID 41375625, 2025). "The inflammatory cytokines IL6 and high-sensitive C-reactive protein (hsCRP) modulate the expression of Tregs and are found to be increased in preeclampsia." (PMID 39328700, 2024). "Our study also revealed a significant increase in inflammatory acute phase reactants like hsCRP and inflammatory cytokine IL-6 in the preeclampsia group (group 3) compared to normal pregnant women (group 2) and non-pregnant women (group 3)." (PMID 39328700, 2024). "Our study shows an increase in sPD-L1 and TGF-β1 and a decrease in Tregs with an increase in inflammatory markers like IL-6 and hsCRP levels in preeclampsia have a potential implication for early diagnosis and management of the condition." (PMID 39328700, 2024). "Our study, showing an increase in sPD-L1 and TGF and a decrease in Tregs with an increase in inflammatory markers like IL-6 and hsCRP levels in preeclampsia, has potential implications for early diagnosis and management of the condition." (PMID 39328700, 2024). "Elevated levels of IL-6 have been previously related to spontaneous abortion, preeclampsia and IUGR, indicating an inflammatory state." (PMID 38474340, 2024). "After adjusting for preeclampsia, a potential confounder in preterm birth pathophysiology, our observations remained consistent, with notably reduced Flt3L and increased IL-6, IL-2 and IL-10 levels." (PMID 39627409, 2024).
preeclampsia (continued). "The subclinical inflammatory process also contributes to the deterioration of placental health, as evidenced by the increased levels of IL-6 detected in patients diagnosed with preeclampsia." (PMID 37168313, 2023). "The current study was conducted to evaluate iron status, hepcidin and IL-6 levels in Sudanese women with preeclampsia." (PMID 36909236, 2023). "Comparing the median (interquartile range) of the iron status indices, hepcidin, and interleukin-6 between women with preeclampsia and controls in Khartoum Sudan, 2020." (PMID 36909236, 2023). "The association between the levels of iron status, hepcidin and interleukin-6 (IL-6), and preeclampsia is not fully understood." (PMID 36909236, 2023). "In contrast, pro-inflammatory IL-6 and anti-inflammatory IL-10 levels were higher in preeclampsia patients compared to normal pregnancies." (PMID 37168313, 2023). "The association between iron status [serum iron, ferritin and total iron-binding capacity (TIBC)], unsaturated iron-binding capacity, hepcidin, interleukin-6 (IL-6) levels and preeclampsia is not fully understood." (PMID 36909236, 2023). "In contrast, we observed higher levels of the pro-inflammatory cytokine interleukin-6 (IL-6) and the anti-inflammatory cytokine interleukin-10 (IL-10) in the preeclampsia group than in the control group." (PMID 37168313, 2023). "Spearman correlation between the iron status, hepcidin, and interleukin-6 in pregnant women with preeclampsia in Khartoum Sudan, 2020." (PMID 36909236, 2023). "During preeclampsia development, maternal inflammatory cytokines (IL‐Iβ, IL‐6, IL‐8 and TNFα) are activated, reducing the expression of eHsp‐27 and increasing the eHsp‐60 and eHsp‐70 levels." (PMID 37002651, 2023). "This increase in pro-inflammatory cytokines, particularly IL-6, is a well-established feature of preeclampsia, as evidenced by a recent study demonstrating elevated levels of IL-6 and its receptor gp130 in endothelial cells from preeclampsia patients." (PMID 37168313, 2023). "TNF-α and IL-6 increase gradually with the severity of preeclampsia from gestational hypertension to mild preeclampsia and severe preeclampsia." (PMID 37887854, 2023). "A total of 9–16 years postpartum plasma level of IL-6 was higher in the early-onset preeclampsia group than in the uncomplicated pregnancy group." (PMID 37887854, 2023). "Implications of IL-6 and CXCL8 in pregnancy-associated pathological conditions, such as pregnancy loss, preeclampsia, gestational diabetes mellitus, and infection/inflammation have been reported." (PMID 37122732, 2023). "In this study, women with preeclampsia had levels of iron homeostasis parameters, hepcidin and IL-6 similar to those observed in healthy pregnant women." (PMID 36909236, 2023). "ASA administration results in the downregulation of the transcription of the pro-inflammatory cytokines TNFα, IFN-γ, IL1, IL6, and IL8, whose genes are regulated by NFĸB; all of these cytokines are strongly linked with the pathomechanism of preeclampsia." (PMID 35270023, 2022). "In order to determine if PDMSCs-CM treatment was effective also at the placental level, we evaluated placental expression of sFlt-1, TNF-α, and IL-6, key hallmarks of preeclampsia, in CM and control mice." (PMID 35163594, 2022). "It should be noted here that there is some controversy about the relevance of IL6 in the context of preeclampsia." (PMID 36009326, 2022). "In our study, we found that regulation of interleukin-6–mediated signaling pathway was enriched in preeclampsia." (PMID 36061193, 2022). "SIRT1 decreases the levels of HMGB1 and HSP70 released from IL-6 induced human umbilical vein endothelial cells (HUVECs) and preeclampsia patient serum." (PMID 35030965, 2022). "The same was observed for interleukin 6 (IL-6), with this marker being significantly increased in the group of women with preeclampsia (p < 0.002)." (PMID 36034841, 2022).
preeclampsia (continued). "The same was observed for another important inflammatory marker, interleukin 6, which was significantly increased in women with preeclampsia (p < 0.0002)." (PMID 36034841, 2022). "A number of factors found in preeclampsia, such as the inflammatory cytokines IL-6 and TNFα, disrupt placental function, resulting in the production of toxic EVs." (PMID 34440672, 2021). "This increased IL-6 and sgp130 production and decreased sIL-6R production in cells from preeclampsia were also shown to be time-dependent." (PMID 35366257, 2021). "We show that cytokines TNF-α, IL-6, and IL-35 are elevated, and IL-10 is reduced in the sera of preterm preeclampsia cohort as compared to control preterm cohort, suggesting a role of chronic inflammation in disease pathology." (PMID 34195300, 2021). "The phenomenon of increased IL-6 and sgp130 production by endothelial cells is even more interesting in preeclampsia." (PMID 35366257, 2021). "Our results have demonstrated that L-NAME- induced preeclampsia like rat model showed oxidative stress and inflammatory changes notified by elevated serum IL-6 and MDA levels." (PMID 33850656, 2021). "We prospectively examined a cohort of maternal-infant dyads with preeclampsia for maternal inflammatory cytokines at time of preeclampsia diagnosis and delivery, and fetal cord blood cytokines (IL-1β, IL-6, IL-8, and TNF-α)." (PMID 34780565, 2021). "Decreased levels of anti-inflammatory cytokines (IL-10, IL-4) and increased pro-inflammatory cytokines (TNF-α, IL-6) in the circulation and placental tissue support the inflammatory background of preeclampsia." (PMID 35004644, 2021). "Proinflammatory cytokines (TNF-α, IFN-γ, IL-2, IL-8, and IL-6) are significantly elevated in preeclampsia." (PMID 33680514, 2021). "Endothelial cells from preeclampsia produced significantly more IL-6 and sgp130, and neutrophils from preeclampsia produced significantly less sIL-6R than normal pregnancy cells." (PMID 35366257, 2021). "The potential role of circulating sIL-6R and sgp130, and their ratio to IL-6 as biomarkers of increased inflammatory response in preeclampsia or cardiovascular diseases, warrants further investigation." (PMID 35366257, 2021). "We found that compared to the cells from normal pregnancies, neutrophils from preeclampsia produced significantly less sIL-6R, p < 0.05 and that endothelial cells from preeclampsia produced significantly more IL-6, p < 0.01 and sgp130, p < 0.05." (PMID 35366257, 2021). "When women with preeclampsia were compared to normotensive women there was a 2.1-fold increase in IL-6 (95% CI 1.18–3.85, p = 0.024) and a 1.7-fold increase in IL-8 (95% CI 1.03–2.79, p = 0.036)." (PMID 34831266, 2021). "Interleukin-6 (IL-6) is elevated in patients with preeclampsia compared to women with normal pregnancy." (PMID 34681861, 2021). "From the studies examined in this review, those consisting of larger cohorts have shown significantly higher IL-6 concentrations in preeclampsia compared to controls." (PMID 33680514, 2021). "Dramatic upregulation of TNF‐α, IL‐6, and IL‐1β was observed in placental tissues from preeclampsia patients compared to healthy donors." (PMID 34089575, 2021). "During pregnancy, maternal IL-6 and sgp130 levels were increased, but sIL-6R levels were decreased, in women with preeclampsia compared to normotensive pregnant women." (PMID 35366257, 2021). "This concept is well supported by our findings of increased IL-6 and sgp130 production by preeclamptic HUVECs and elevated maternal levels of IL-6 and sgp130 in women with preeclampsia." (PMID 35366257, 2021). "In women who went onto developing preeclampsia, another study found that those with samples collected in the first trimester had significantly higher IL-12 and IL-6 concentrations while women with second trimester serum samples had higher IL-8." (PMID 33680514, 2021).
preeclampsia (continued). "Second, we found that neutrophils from women with preeclampsia produced significantly less sIL-6R, and endothelial cells from women with preeclampsia produced significantly more IL-6 and sgp130 than cells from normal pregnant subjects." (PMID 35366257, 2021). "We previously reported that maternal levels of IL-6 and sgp130 are significantly higher in women with preeclampsia than in women with normal pregnancy." (PMID 35366257, 2021). "IL-6 is reportedly related to maternal preeclampsia and HDP accompanied by proteinuria or maternal organ damage." (PMID 33211747, 2020). "The umbilical serum level of inflammatory markers (interleukin-6, interleukin-8, and tumor necrosis factor-alpha) in pregnancies complicated by preeclampsia was significantly increased compared with normal pregnancies." (PMID 32587622, 2020). "In preeclampsia, the frequency of circulating Tfh cells and the level of IL-21 and IL-6 were higher compared to healthy pregnant women; this is probably associated with the production of disorder-specific autoantibodies." (PMID 32265904, 2020). "Previous studies have shown that autophagy, apoptosis, and necrosis occur in trophoblast cells and that secretion of inflammatory factors, especially IL-6, increases dramatically in preeclampsia." (PMID 33659272, 2020). "This is plausible since preeclampsia patients have increased circulating levels of tumor necrosis factor alpha (TNFα), interleukin (IL)-2, IL-6, and IL-17." (PMID 31434191, 2019). "Not only the baseline release of pro-inflammatory cytokines from peripheral blood monocytes was increased in preeclampsia, LPS-induced TNF-α, IL-1β, and IL-6 release was also enhanced in women with preeclampsia." (PMID 31138166, 2019). "Meta-analyses have described a potential association between preeclampsia and elevated levels of serum triglycerides, cholesterol, and inflammatory markers including CRP, IL-6, IL-8, and TNFα, some of which precede the onset of preeclampsia." (PMID 31590294, 2019). "Worse diastolic LV function is accompanied by higher plasma levels of IL-6 and sICAM-1, which are known to be elevated during preeclampsia." (PMID 29894501, 2018). "These elevated markers were also found in our patients with a history of preeclampsia, with higher levels of IL-6 and sICAM-1." (PMID 29894501, 2018). "Raised IL-6 has been associated previously with later development of GDM and has been described in preeclampsia at the time of disease in unselected populations." (PMID 30177064, 2018). "Plasma level of IL-6 was higher in women with a history of early-onset preeclampsia than in women with a history of uncomplicated pregnancy." (PMID 29894501, 2018). "Women with a history of preeclampsia had higher body mass index (p = 0.006), blood pressure (p<0.001) and plasma levels of interleukin-6 (p = 0.005) and soluble intercellular adhesion molecule-1 (sICAM-1) (p = 0.014)." (PMID 29894501, 2018). "In this study, wefound that RUPP rats, a commonly used animal model of preeclampsia, have severemyocardial damage, which is attributed to the high expression of IL-6." (PMID 29898033, 2018). "Preeclampsia is characterised by significantly higher levels of pro-inflammatory cytokines such as IL-6 and TNF-α, when compared with normal pregnant women." (PMID 28103790, 2017). "In the current study, we observed elevated concentrations of sFlt-1, hsCRP, and IL-6 in early preeclampsia, late preeclampsia, and IUGR groups compared with the control group." (PMID 27760191, 2016). "The aim of our study was to analyse the potential role of sFlt1, PlGF, sEng, IL-6, and IL-16 in predicting PE and eventually to find a practical panel of biomarkers useful in early diagnosis of preeclampsia." (PMID 27799724, 2016). "In those studies, IL-6 levels were higher in the preeclampsia and IUGR groups compared with the control group." (PMID 27760191, 2016).
preeclampsia (continued). "Pro-inflammatory cytokines IL-6 and IL-8 are increased in maternal serum from women with preeclampsia as compared with normal pregnancy." (PMID 26247971, 2015). "In previous studies, it has been confirmed that patients with preeclampsia have significantly higher serum concentrations of IP-10 and IL-6 than normal pregnant women." (PMID 24659862, 2014). "Interleukin-6 (IL-6), a pro-inflammatory cytokine secreted by both activated leukocytes and endothelial cells, is also elevated in serum and plasma of women with severe preeclampsia." (PMID 22398973, 2012). "In the present study, we have evaluated maternal TNF-alpha and IL-6 plasma levels in normotensive pregnant women as well as in women with preeclampsia." (PMID 21253506, 2010). "An interesting finding of this study is that elevated circulating TNF-alpha and IL-6 levels were detected long after delivery in women with preeclampsia." (PMID 21253506, 2010). "Median levels of CRP, fibrinogen, and IL-6 were significantly higher in women with a history of early-onset preeclampsia." (PMID 18382655, 2008). "The results of this study show that IL-6 as a pro-inflammatory cytokine is present in higher concentration in women with preeclampsia." (PMID 16259641, 2005). "Recent studies have shown that amniotic fluid IL-6 is decreased in pregnancies complicated by preeclampsia and placental IL-6 production is decreased in these patients." (PMID 16259641, 2005). "Both interleukin-6 (IL-6) and interleukin-8 (IL-8) are immune factors, and studies have shown that they influence the pathological processes of pregnancy-related diseases, including preeclampsia, GDM, and inflammation." (PMID 41334450, 2025). "Preeclampsia is associated with an exacerbated inflammatory response that may lead to a release of pro-inflammatory cytokines, including TNF-α, interleukin-6 (IL-6), interleukin-8 (IL-8), and interleukin-1 beta (IL-1β)." (PMID 40109359, 2025). "We performed a secondary analysis of a randomized, placebo-controlled trial of LDA (60 mg daily) for preeclampsia prevention in high-risk individuals (N = 524) on pregnancy outcomes and concentrations of PLGF, IL-2, IL-6, thromboxane B2 (TXB2), sTNF-R1 and sTNF-R2 from maternal serum." (PMID 38851168, 2024). "However, the analysis showed increased levels of IL-6 in women with preeclampsia compared to healthy women." (PMID 38893732, 2024). "IL-6 is a proinflammatory cytokine secreted excessively by maternal immune cells in preeclampsia." (PMID 37887854, 2023). "Regarding changes in the cytokine profile in preeclampsia, there is evidence that the levels of pro-inflammatory cytokines, namely TNF-α and IL-6, are increased in preeclampsia, while the concentrations of anti-inflammatory cytokines, namely IL-4 and IL-10, are decreased." (PMID 37168313, 2023). "In Pinheiro article also non-association between TNF-α (− 308 G → A), IL-6 (− 174 G → C), or IL-10 (− 1082 G → A) polymorphisms and preeclampsia was reported." (PMID 38057745, 2023). "Some previous studies have reported higher levels of IL-6 in women with preeclampsia." (PMID 36909236, 2023). "In addition to the elevated levels of pro-inflammatory cytokine IL-6, our study also found elevated levels of anti-inflammatory cytokine IL-10 in women with preeclampsia." (PMID 37168313, 2023). "Notably, we discovered that pro-inflammatory IL-6 and anti-inflammatory IL-10 levels were higher in women with preeclampsia compared to women with uncomplicated pregnancies." (PMID 37168313, 2023). "Given inflammation and placental hypoxia play crucial role in pathophysiology of preeclampsia, we examined the effect of pro-inflammatory cytokines (IL-6 and TNFα) and hypoxia on LGALS3 and LGALS3BP mRNA expression in placental cytotrophoblast and syncytiotrophoblast cells." (PMID 36311252, 2022).